ADH5 (alcohol dehydrogenase 5 (class III), chi polypeptide)
Description:
Catalyzes the oxidation of long-chain primary alcohols and the oxidation of S-(hydroxymethyl) glutathione. Also oxidizes long chain omega-hydroxy fatty acids, such as 20-HETE, producing both the intermediate aldehyde, 20-oxoarachidonate and the end product, a dicarboxylic acid, (5Z,8Z,11Z,14Z)-eicosatetraenedioate. Class-III ADH is remarkably ineffective in oxidizing ethanol. Required for clearance of cellular formaldehyde, a cytotoxic and carcinogenic metabolite that induces DNA damage. Also acts as a S-nitroso-glutathione reductase by catalyzing the NADH-dependent reduction of S-nitrosoglutathione, thereby regulating protein S-nitrosylation (By similarity).
Synonyms: FALDH; FDH; GSH-FDH; ADHX; ADH-3; GSNOR; AMEDS; BMFS7; HEL-S-60p
Tractability: Small molecule: an approved drug acts on it; a structure with a bound ligand is known; a high-quality ligand is known; it has a high-quality binding pocket; it belongs to a druggable protein family. PROTAC: ubiquitination databases record sites on it; its protein half-life has been measured; a small molecule that binds it is known.
Target class: Enzyme; Oxidoreductase
Gene: Protein-coding gene on chromosome 4 (99,070,978 to 99,088,801, reverse strand). Ensembl gene ENSG00000197894.
Subcellular location: Cytoplasm
Pathways (Reactome):
Metabolism: Ethanol oxidation
Gene Ontology:
Molecular function: alcohol dehydrogenase (NAD+) activity; fatty acid binding; formaldehyde dehydrogenase (NAD+) activity; S-(hydroxymethyl)glutathione dehydrogenase (NAD+) activity; S-(hydroxymethyl)glutathione dehydrogenase (NADP+) activity; zinc ion binding; electron transfer activity; S-(hydroxymethyl)glutathione dehydrogenase [NAD(P)+] activity; S-nitrosoglutathione reductase (NADH) activity; long-chain fatty aldehyde dehydrogenase (NAD+) activity; oxidoreductase activity
Biological process: fatty acid omega-oxidation; response to redox state; formaldehyde catabolic process
Cellular component: extracellular exosome; cytosol; cytoplasm
Genetic constraint (gnomAD): Loss-of-function variants: 27 observed, 31.26 expected, observed/expected ratio (o/e) 0.86, 90% interval 0.64 to 1.19. The upper end of that interval is the gene's LOEUF score, 1.19, which puts it in group 5 of 6, group 1 being the genes least tolerant of losing a copy. Missense variants: 311 observed, 398.06 expected, observed/expected ratio (o/e) 0.78, 90% interval 0.71 to 0.86. Synonymous variants: 108 observed, 135.88 expected, observed/expected ratio (o/e) 0.79, 90% interval 0.68 to 0.93.
Homologues: Orthologues: chimpanzee ADH5 (99% identical), macaque ADH5 (98% identical), pig ADH5 (95% identical), rabbit ADH5 (94% identical), guinea pig ADH5 (93% identical), rat Adh5 (93% identical), mouse Adh5 (92% identical), tropical clawed frog adh5 (85% identical), zebrafish zgc:77938 (64% identical), zebrafish adh5l (64% identical), zebrafish adh8a (62% identical), zebrafish adh8b (56% identical), and 5 more. Paralogues in human: ADH1A (63% identical), ADH1B (63% identical), ADH1C (63% identical), ADH4 (62% identical), ADH7 (60% identical), ADH6 (59% identical), CRYZ (21% identical), MECR (20% identical), VAT1 (20% identical), RTN4IP1 (20% identical), SORD (20% identical), VAT1L (19% identical), and 5 more.
Diseases named in the same sentence as ADH5 in open-access papers:
ADH5 is named in the same sentence as 124 diseases in open-access papers, as found by Europe PMC text mining. Sharing a sentence is not in itself a finding about the gene and the disease. The quoted sentences say what the papers report.
hepatocellular carcinoma (12 papers, 2012 to 2024). A malignant tumor that arises from hepatocytes. "Research has demonstrated that the downregulation of ADH5 is a feature of primary hepatocellular carcinoma, and its pharmacological inhibition by inducible nitric oxide synthase (iNOS) presents a promising treatment option for individuals with primary hepatocellular carcinoma." (PMID 38600527, 2024).
Fanconi anemia (10 papers, 2021 to 2025). Fanconi anemia (FA) is a hereditary DNA repair disorder characterized by progressive pancytopenia with bone marrow failure, variable congenital malformations and predisposition to develop hematological or solid tumors. "Using a sensitized cellular system deficient in the Fanconi anemia pathway, we demonstrated that ADH5 and the ALDH3-family of enzymes protect mammalian keratinocytes from endogenous DNA damage." (PMID 41292832, 2025). "High levels of reactive aldehydes overwhelm the detoxification capacity of ALDH2/ADH5 and result in DNA interstrand crosslinks (ICLs) that require functional Fanconi anemia pathway for repair." (PMID 40854122, 2025). "FA has emerged as a fundamental contributor to human disorders such as Fanconi anemia, Cockayne syndrome, and AMeDS, which are caused by mutations in FANC genes, CSB or CSA, and ADH5 and ALDH2, respectively." (PMID 38894680, 2024). "Tier 1 involves aldehyde detoxification enzymes (ALDH2 and ADH5) followed by tier 2 Fanconi anemia DNA damage repair pathways to repair aldehyde-induced DNA damage." (PMID 38963759, 2024). "HSCs produce genotoxic formaldehyde that requires protection by the detoxification enzymes ALDH2 and ADH5 and the Fanconi anemia (FA) DNA repair pathway." (PMID 37348497, 2023). "The level of activity of the Fanconi Anemia pathway appears to be sufficient to sustain primordial germ cell numbers, at least in inbred mice, since single mutants of Aldh2 and Adh5 have wild-type levels of primordial germ cells by embryonic day 12.5." (PMID 33500205, 2021). "Specifically, in mice, the Fanconi anemia DNA repair pathway factor D2 (Fancd2) and the transcription coupled factor Csb have been shown to genetically interact with Adh5, indicating a central role of these DNA repair factors in counteracting the genotoxicity of cellular FA in animals." (PMID 38894680, 2024). "Notably, the failure to detoxify endogenously produced aldehydes in patients with a combination of the ADH5 allele and ALDH2 causes Fanconi anemia, underscoring the critical role of ALDH in the hematopoietic system." (PMID 38226171, 2024). "In primordial germ cells, endogenous DNA crosslinks that are substrates for Fanconi Anemia-mediated repair may derive from reactive aldehydes, since Fanca becomes critical in Aldh2 and Adh5 mutants that accumulate endogenous reactive aldehydes." (PMID 33500205, 2021). "Furthermore, the adh-5;alh-1(RNAi) model offers a platform to understand the genotoxic mechanisms driving anomalies observed in rare progeroid conditions, such as AMeDS, and possibly Cockayne syndrome or Fanconi anemia." (PMID 38894680, 2024). "These adverse effects can be scavenged by detoxifying enzymes, which have been the main focus of recent research in patients of a rare hereditary Fanconi anemia and animals with impaired expression of the DDR gene FANCD2 and the detoxifying enzymes ALDH2 and ADH5." (PMID 33573309, 2021).
leukemia (8 papers, 2020 to 2025). A malignant (clonal) hematologic disorder, involving hematopoietic stem cells and characterized by the presence of primitive or atypical myeloid or lymphoid cells in the bone marrow and the blood. "Loss or insufficient activity of ALDH2 and ADH5, which both metabolize formaldehyde, has been linked to early bone marrow failure and the spontaneous development of leukemia in mice and humans with FA pathway deficiency, resulting in a DNA repair defect." (PMID 41292832, 2025). "Similarly, in mouse models of FA, mice with only Fancd2 mutations exhibit a long latency to developing mild hematopoietic stem cell dysfunction, but adding an Adh5 or Aldh2*2 mutation results in bone marrow failure and leukemia." (PMID 40244696, 2025). "We also demonstrate that simultaneous targeting of Polθ and ADH5 or ALDH2 may have therapeutic potential in HR-deficient leukemias, and those harboring high levels of endogenous formaldehyde triggered by OTKs." (PMID 40640557, 2025). "Based on these findings, we postulate that ADH5 and ALDH2 inhibitors enhance the synthetically lethal effect of Polθi against HR-deficient leukemia cells." (PMID 40640557, 2025). "Without enzymes that detoxify formaldehyde, specifically ALDH2 and ADH5, hematopoietic cells die or transform into leukemia." (PMID 41292832, 2025). "We postulate that the interdependence between Polθ and ALDH2/ADH5 in protecting leukemia cells from high levels of endogenous formaldehyde creates a translational opportunity." (PMID 40640557, 2025). "We find that mice lacking two aldehyde detoxifying enzymes, mitochondrial ALDH2 and cytoplasmic ADH5, have greatly shortened lifespans and develop leukemia." (PMID 33147438, 2020). "Mice lacking both ALDH2 and ADH5 develop leukaemia and have shorter lifespans, and, despite active DNA repair, bone marrow-derived progenitors acquire a formaldehyde-associated mutation signature that resembles human cancer mutation signatures associated with aging." (PMID 35485397, 2022). "Animal experiments confirmed that mice lacking ADH5 and ALDH2 have greatly shortened lifespans and develop leukemia in vivo." (PMID 34778061, 2021).
breast carcinoma (7 papers, 2018 to 2026). "The staining of ADH5 might be useful in classifying the subtypes of breast cancer." (PMID 35847355, 2022). "Moreover, several Tip60-targeted Khib were identified on cancer biomarkers, such as plectin (PLEC, related to ovarian cancer), alcohol dehydrogenase class-3 (ADH5, related to breast cancer), and PARK7 (related to lung cancer), which therefore links Tip60 and the Khib pathway to cancer." (PMID 35178156, 2022). "The gene-gene interactions of deregulated glucose related genes in breast cancer, and it was found that deregulated glucose related genes show high interactions with PFKFB2, PFKFB4, FBP2, PCK2, ADH5 and other genes involved in glucose metabolism." (PMID 38173442, 2024). "Utilizing the public CRISPR knockout screening datasets sourced from DepMap, we further supported our hypothesis that the essential roles of ADH5, ALDH1B1, and ALDH7A1 in breast cancer cell growth and development." (PMID 42196229, 2026).
bone marrow failure (5 papers, 2015 to 2025). "Recent works indicated that interruption of ALDH2 or ADH5, the major enzymes for FA degradation, may cause the accumulation of DNA damage and related diseases such as bone marrow failure, as well as dysfunction of liver and kidney." (PMID 33495458, 2021). "Two enzymes, ADH5 and ALDH2, are critical in clearance of formaldehyde, whose loss results in a bone marrow failure and leukemia syndrome of purely metabolic origin." (PMID 33147438, 2020). "Adh5−/−Fancd2−/− mice reveal an essential requirement for these protection mechanisms in hematopoietic stem cells (HSCs), leading to their depletion and precipitating bone marrow failure." (PMID 26412304, 2015). "Through a combination of whole-exome sequencing (WES) and targeted exome sequencing of the ADH5 gene, we sequenced children and young adults with bone marrow failure of unknown etiology from the Japanese Cancer Research Resources Bank (JCRB; Osaka, Japan) and our local centers." (PMID 33147438, 2020). "The more rapid onset of bone marrow failure in Adh5−/−Fancd2−/− compared to Aldh2−/−Fancd2−/− mice, in addition to the involvement of additional tissues, suggests that the compound(s) detoxified by ADH5 are much more potent or abundant genotoxins than those cleared by ALDH2." (PMID 26412304, 2015).
Obesity (5 papers, 2021 to 2025). Accumulation of substantial excess body fat. "Recently we demonstrated that BAT ADH5 protects against obesity-associated metabolic dysfunction." (PMID 40631281, 2025). "Low protein abundance of ADH5, thus, suggest that oxidative stress together with other biological process as inflammation are closely tied to reproductive dysfunction in men with obesity, compromising their fertility." (PMID 38703299, 2024). "A previous study in obesity has shown that ADH5 transcript is significantly increased in brown adipose tissue (BAT) from patients with obesity, suggesting its role in protecting BAT against obesity-associated metabolic dysfunction." (PMID 38703299, 2024). "Additionally, patients with obesity have reduced abundance of ADH5 in platelets." (PMID 38703299, 2024). "We previously showed obesity suppresses BAT HSF1 and the HSF1-induced ADH5 expression." (PMID 40631281, 2025).
AMeD syndrome (4 papers, 2022 to 2025). "This indicates that early diagnosis and treatment is important in AMeD syndrome with heterozygous or compound heterozygous ADH5 and ALDH2." (PMID 39211293, 2024). "Inherited mutations in the FA-detoxifying enzymes ADH5 and ALDH2 genes lead to FA overload in the severe multisystem AMeD syndrome." (PMID 38894680, 2024). "AMeD syndrome is characterized by aplastic anemia, mental retardation, short stature, and microcephaly and is caused by digenic mutations in the aldehyde dehydrogenase 2 (ALDH2) and alcohol dehydrogenase 5 (ADH5) genes." (PMID 39211293, 2024).
Cockayne syndrome (4 papers, 2022 to 2025). A multisystem condition characterized by short stature, a characteristic facial appearance, premature aging, photosensitivity, progressive neurological dysfunction, and intellectual deficit. "Subsequent elimination of CSB in these ADH5−/− mice induced features reminiscent of Cockayne syndrome." (PMID 41333433, 2025). "In this study, the authors identified endogenous formaldehyde as the cause of transcriptional stress and demonstrated that mice with deletions in the adh5 and Csb (Adh5−/−Csbm/m) genes exhibited features akin to those seen in human Cockayne syndrome, including cachexia and severe kidney failure." (PMID 35834102, 2022).
alcohol (3 papers, 2017 to 2022).
aplastic anemia (3 papers, 2023 to 2024). Anemia resulting from bone marrow failure (aplastic or hypoplastic bone marrow). "AP39P cells, skin fibroblasts from a patient with aplastic anemia, mental retardation, and dwarfism syndrome, harbored compound heterozygous mutations in the alcohol dehydrogenase 5 (ADH5) gene (c.564+1G>A, c.832G>C) and a heterozygous mutation in aldehyde dehydrogenase 245,46." (PMID 37714828, 2023). "In line with this hypothesis, it has been shown that increased aldehyde levels due to mutations in both ALDH2 and ADH5 result in aplastic anaemia, mental retardation and dwarfism (AMed) syndrome that is characterized by neuronal clinical features that overlap with CS52,72." (PMID 38600236, 2024).
gastric cancer (3 papers, 2020 to 2024). A primary or metastatic malignant neoplasm involving the stomach. "Alcohol dehydrogenase 5 (ADH5) is considered an important tumor suppressor in gastric cancer and non-small cell lung cancer, playing an anti-tumor role." (PMID 38586328, 2024). "At the same time, ADH5 is also considered an important tumor suppressor factor for gastric cancer." (PMID 36387908, 2022). "Whereas, the expression of ADH5 were significantly upregulated in HCC tissues compared to normal liver tissues, consistent with what is already known in NSCLC, gastric cancer, and pancreatic adenocarcinoma." (PMID 33287761, 2020).
kidney failure (3 papers, 2021 to 2024). An acute or chronic condition that is characterized by the inability of the kidneys to adequately filter the blood. "Moreover, neurodegeneration and kidney failure were observed in mice lacking both Adh5 and a TCR gene, Csb35." (PMID 38600234, 2024).
lung carcinoma (3 papers, 2012 to 2022). "For lung cancer patients, high expression of ADH1B, ADH1C, ADH4, and ADH5 genes can achieve a better prognosis." (PMID 36212135, 2022).
alcohol abuse (2 papers, 2018 to 2025). The use of alcoholic beverages to excess, either on individual occasions ("binge drinking") or as a regular practice. "We identified one candidate causal protein for Parkinson’s disease (GBA1) and two for alcohol use disorder (METAP1 and ADH5) in participants of African ancestry." (PMID 40921788, 2025). "Third, we identified two candidate causal proteins specific to individuals of African ancestry in alcohol use disorder (ADH5 and METAP1) despite lower statistical power from the corresponding GWAS and reference proteogenomic data." (PMID 40921788, 2025).
autoimmune disease (2 papers, 2019 to 2021). A disorder resulting from loss of function or tissue destruction of an organ or multiple organs, arising from humoral or cellular immune responses of the individual to their own tissue constituents. "GSNOR (ADH5) is generally found to be elevated in respiratory, cardiovascular, smooth muscle, and autoimmune disease states." (PMID 31766125, 2019).
bone marrow failure syndrome (2 papers, 2020 to 2024). "We discovered seven human families carrying genetic defects in ALDH2 and ADH5, presenting as a new bone marrow failure syndrome that is solely driven by formaldehyde accumulation." (PMID 33147438, 2020).
colitis (2 papers, 2014 to 2019). Inflammation of the colon. "RT‐PCR and IHC analysis validated that TOE up‐regulated the expression of Adh5, Aldh3a2 and Acox3, but down‐regulated the expression of CCL20, CXCL5, CCR6 and CXCL1 in DSS‐induced colitis." (PMID 31565850, 2019).
liver cancer (2 papers, 2012 to 2015). An epithelial or non-epithelial malignant neoplasm that arises from the liver. "Adh5−/− mice are susceptible to developing liver cancer following exposure to the carcinogen diethylnitrosamine because of nitrosylation and inactivation of the DNA repair enzyme O6-alkylguanine-DNA alkyltransferase (AGT)." (PMID 26412304, 2015).
lymphopenia (2 papers, 2020 to 2021). Reduction in the number of lymphocytes. "In summary, combined inactivation of the aldehyde-clearing enzymes ALDH2 and ADH5 leads to perinatal lethality, growth failure, lymphopenia, and lymphoid malignancies." (PMID 33147438, 2020).
myelodysplastic syndrome (2 papers, 2023 to 2024). A clonal hematopoietic disorder characterized by dysplasia and ineffective hematopoiesis in one or more of the hematopoietic cell lines. "In 2020, a digenic ADH5/ALD2H2 deficiency causing severe BMF, early-onset myelodysplastic syndrome (MDS), short stature and intellectual disability was connected to the inability to detoxify formaldehyde." (PMID 37091189, 2023).
Pancytopenia (2 papers, 2021 to 2025). An abnormal reduction in numbers of all blood cell types (red blood cells, white blood cells, and platelets). "While mice with combined deficiency in ADH5 and the corresponding repair gene FANCD2 would result in blood pancytopenia, the reduction of bone marrow cellularity and the acceleration of HSC attrition cause failure to sustain hematopoiesis." (PMID 33573309, 2021).
alcoholic hepatitis (1 paper, 2024). Acute hepatitis resulting from ingestion of alcohol. "However, our analysis of the GSE28691 database showed that ADH1A and ADH1C were downregulated in liver tissues of patients with alcoholic hepatitis, while ADH1B and ADH5 showed no significant changes." (PMID 39044161, 2024).
anaemia (1 paper, 2024). "Moreover, because Adh5−/−Aldh2+/KICsb−/− mice exhibited anaemia, similar to Adh5−/−Aldh2KI/KI mice, we conducted flow cytometric analyses of bone marrow cells from these animals." (PMID 38600234, 2024).
Cachexia (1 paper, 2022). Severe weight loss, wasting of muscle, loss of appetite, and general debility related to a chronic disease. "Remarkably, treatment of Adh5−/−Csbm/m mice with an anti‐GDF15 antibody completely prevented DNA damage/GDF15‐ induced cachexia." (PMID 35834102, 2022).
chronic kidney failure (1 paper, 2015). "In addition, humans lacking the FAN1 nuclease develop chronic kidney failure with features similar to the Adh5−/−Fancd2−/− mice that we report here." (PMID 26412304, 2015).